SLC12A8 (solute carrier family 12 member 8)
Description:
Cation/chloride cotransporter that may play a role in the control of keratinocyte proliferation.
Synonyms: CCC9
Tractability: Antibody: UniProt predicts a signal peptide or a membrane-spanning region. PROTAC: ubiquitination databases record sites on it.
Safety:
Unwanted effects reported when the protein is acted on. In parentheses: how it was acted on, where the effect was seen, and who reports it.
paradoxical psoriasiform reactions (source: ClinPGx)
Gene: Protein-coding gene on chromosome 3 (125,082,636 to 125,213,229, reverse strand). Ensembl gene ENSG00000221955.
Subcellular location: Membrane
Subcellular location (Human Protein Atlas): Nucleoplasm
Gene Ontology:
Molecular function: protein binding; chloride:monoatomic cation symporter activity
Biological process: potassium ion transmembrane transport; chloride transmembrane transport; monoatomic ion transport; transmembrane transport
Cellular component: apical plasma membrane; membrane
Genetic constraint (gnomAD): Loss-of-function variants: 59 observed, 66.32 expected, observed/expected ratio (o/e) 0.89, 90% interval 0.72 to 1.11. The upper end of that interval is the gene's LOEUF score, 1.11, which puts it in group 4 of 6, group 1 being the genes least tolerant of losing a copy. Missense variants: 801 observed, 866.2 expected, observed/expected ratio (o/e) 0.92, 90% interval 0.87 to 0.98. Synonymous variants: 343 observed, 362.35 expected, observed/expected ratio (o/e) 0.95, 90% interval 0.87 to 1.03.
Homologues: Orthologues: chimpanzee SLC12A8 (98% identical), macaque SLC12A8 (96% identical), dog SLC12A8 (87% identical), pig SLC12A8 (87% identical), rabbit SLC12A8 (87% identical), mouse Slc12a8 (80% identical), guinea pig SLC12A8 (79% identical), rat Slc12a8 (77% identical), tropical clawed frog SLC12A8 (61% identical), zebrafish slc12a8 (59% identical), Drosophila melanogaster CG12773 (37% identical), Caenorhabditis elegans F10E7.9 (31% identical). Paralogues in human: SLC12A2 (28% identical), SLC12A1 (27% identical), SLC12A3 (25% identical), SLC12A5 (22% identical), SLC12A4 (22% identical), SLC12A6 (21% identical), SLC12A7 (21% identical), SLC12A9 (19% identical).
Diseases named in the same sentence as SLC12A8 in open-access papers:
SLC12A8 is named in the same sentence as 16 diseases in open-access papers, as found by Europe PMC text mining. Sharing a sentence is not in itself a finding about the gene and the disease. The quoted sentences say what the papers report.
psoriasis (11 papers, 2005 to 2025). An autoimmune condition characterized by red, well-delineated plaques with silvery scales that are usually on the extensor surfaces and scalp. "SLC12A8 is thought to be a candidate for psoriasis susceptibility." (PMID 33364434, 2021). "SNPs in TLR2, TNF, SLC12A8, ZNF816A and TNFAIP3 genes were associated with 3-month response (measured as PASI90 and absolute PASI < 1) to Secukinumab and Ixekinumab in 19 psoriasis patients." (PMID 41153404, 2025). "Certain SNPs in genes like IL23R, FBXL19, CTLA4, SLC12A8, TAP1, and others predispose individuals to paradoxical psoriasis." (PMID 39000125, 2024). "A previous study from our laboratory found five SNPs (rs11209026 in IL23R, rs10782001 in FBXL19, rs3087243 in CTLA4, rs651630 in SLC12A8, and rs1800453 in TAP1) associated with anti-TNF-induced paradoxical psoriasis reactions." (PMID 36143237, 2022). "On the basis of current researches, we found that the upregulation of SLC12A8 was related to psoriasis, psoriatic arthritis, atopic dermatitis, and breast cancer." (PMID 33364434, 2021). "Other transporter genes (SLC12A8 and SLC9A3R1) have also been linked to susceptibility to other autoimmune diseases such as psoriasis." (PMID 15642130, 2005). "The SLC12A8 rs651630 (G > A) polymorphism was evaluated in a study of predictive biomarkers for the risk of developing toxicity and/or paradoxical psoriasis due to anti-TNF drugs in Spanish patients with moderate-to-severe psoriasis (n = 161)." (PMID 33921427, 2021).
bladder cancer (5 papers, 2021 to 2025). "Next, the Transwell assays were used to detect the association between SLC12A8 expression and bladder cancer metastasis." (PMID 33364434, 2021). "In addition, to explore whether SLC12A8 expression levels were associated with prognosis of bladder cancer, the Kaplan–Maier analysis and log-rank comparison were carried out." (PMID 33364434, 2021). "SLC12A8 is highly correlated with the oncogenesis and progression of bladder cancer and promotes the expression of EMT protein markers, including β-catenin, vimentin, snail, and slug, through the JAK/STAT pathway." (PMID 40299526, 2025). "The regulatory role of solute carrier family 12 members in tumor progression and immune responses has been rarely reported, and recent studies have found that SLC12A8 plays a critical role in bladder cancer progression and EMT." (PMID 35372048, 2022). "How SLC12A8 affects the progression of bladder cancer also requires further exploration, which is the next research topic we will carry out." (PMID 33364434, 2021). "The bladder cancer patients were divided into SLC12A8 high expression group (n = 202) and SLC12A8 low expression group (n = 203) according to the median value of SLC12A8 expression." (PMID 33364434, 2021). "Up to now, this is the first study reporting that upregulation of SLC12A8 promoted the development and metastasis of the bladder cancer and correlated with poor prognosis." (PMID 33364434, 2021). "But to our knowledge, no report has been published about the biological function and the regulation of SLC12A8 expression in bladder cancer." (PMID 33364434, 2021). "Our research demonstrated that SLC12A8 was closely related to the malignant degree of bladder cancer and affect the patients’ survival." (PMID 33364434, 2021). "Rely on the TCGA database, the SLC12A8 expression level was demonstrated notably higher in bladder cancer tissue compared with normal tissue (p = 0.0005)." (PMID 33364434, 2021). "SLC12A8 expression was notably correlated with the age, pathological stage, T-stage, and lymph node metastasis of bladder cancer patients." (PMID 33364434, 2021). "The Cox regression analysis results showed that the SLC12A8 expression, Clinical stage, T stage, lymph node, metastasis, and age were notably correlated with OS of bladder cancer patients." (PMID 33364434, 2021). "The analysis based on the TCGA and ONCOMINE database revealed that the expression of SLC12A8 in bladder cancer was notably increased compared with the normal group." (PMID 33364434, 2021). "The results demonstrated that higher SLC12A8 expression level was correlated with shorter OS in bladder cancer patients (p = 0.043)." (PMID 33364434, 2021). "Solute carrier family 12 member 8 has been reported to be upregulated in bladder cancer and related to patient prognosis and tumor immune cell infiltration." (PMID 34486492, 2021). "We used CIBERSORT and TIMER 2.0 to analyze the tumor immune cell infiltration of SLC12A8 in bladder cancer." (PMID 34365894, 2021). "In the case of downregulated SLC12A8 expression, the proliferative, invasive, and migratory capacities of bladder cancer cells and the expression of EMT protein markers presented the opposite trend." (PMID 33364434, 2021). "The intention of the present research is to explore the prognostic value and biological function of solute carrier family 12 member 8 (SLC12A8) in bladder cancer." (PMID 33364434, 2021). "In brief, human bladder cancer T24 cells were transfected with si-SLC12A8#1 and si-SLC12A8#2, while 5637 cells were transfected with pcDNA3.1-SLC12A8." (PMID 33364434, 2021). "The invasive ability was 2.37 times of the control group (p < 0.01), while the migratory ability was 1.91 times of the control group (p < 0.01), illustrating that the invasive and migratory capacities of bladder cancer cells were enhanced by SLC12A8 upregulation." (PMID 33364434, 2021).
bladder cancer (continued). "Our research indicated that SLC12A8 upregulation could notably promote the EMT process in bladder cancer, suggesting that SLC12A8 might promote the malignant development of tumor by regulating the EMT process." (PMID 33364434, 2021). "Therefore, SLC12A8 is expected to be an indicator to evaluate the prognosis of bladder cancer patients as well as an effective therapeutic target for bladder cancer treatment." (PMID 33364434, 2021). "This study demonstrated that SLC12A8 was highly correlated with oncogenesis and progression of bladder cancer, indicating that SLC12A8 may be a meaningful biomarker for initial diagnosis and early treatment of bladder cancer." (PMID 33364434, 2021). "However, the expression of SLC12A8 in bladder cancer and its mechanism of action have not been reported." (PMID 33364434, 2021). "Moreover, data from TCGA and GTEx presented the similar result, and SLC12A8 was highly expressed in bladder cancer compared with the normal samples (p = 1.07 × 10−12)." (PMID 33364434, 2021). "The solute carrier family has been reported to play critical roles in the progression of several cancers; however, the relationship between solute carrier family 12 member 8 (SLC12A8) and bladder cancer (BC) has not been clearly confirmed." (PMID 34365894, 2021).
breast carcinoma (2 papers, 2021 to 2026). "Bioinformatic analysis and experimental validation confirmed that high SLC12A8 expression was strongly associated with reduced infiltration and functional inhibition of CD8+ T cells in the tumor microenvironment, particularly in Luminal B breast cancer." (PMID 41795804, 2026). "qPCR was performed to validate SLC12A8 expression in various breast cancer cell lines." (PMID 41795804, 2026). "Mechanistically, SLC12A8 activated the TLR signaling pathway (upregulating TLR2, MyD88, IRAK1, TAK1 in CD8+ T cells), leading to increased PD-1 expression on CD8+ T cells, resulting in their functional exhaustion and enhanced invasive ability of Luminal B breast cancer cells." (PMID 41795804, 2026).
pancreatic cancer (2 papers, 2021 to 2022). "To investigate whether SLC12A8 plays any role in polyamine transport, we first examined the expression and localization of the protein in the different pancreatic cancer cells." (PMID 35260637, 2022).
sarcopenia (2 papers, 2025). Progressive decline in muscle mass due to aging which results in decreased functional capacity of muscles. "Remarkably, LH-specific Slc12a8 overexpression significantly improves energy and carbohydrate expenditure, endurance capacity, muscle mass and force, and the sympathetic nerve-β2AR axis in aged mice, ameliorating age-associated sarcopenia and frailty." (PMID 39870672, 2025). "In this case, it will be of great importance to examine whether NMN could prevent age-associated sarcopenia and frailty through the activation of Slc12a8-positive LH neurons." (PMID 39870672, 2025). "Conversely, overexpression of Slc12a8 in the LH improved age‐associated dysfunction of skeletal muscle, suggesting that dysfunction of Slc12a8 in the LH during aging is involved in the pathogenesis of sarcopenia." (PMID 40955861, 2025). "Given the expression of Slc12a8 decreases in the LH over age, it will also be of great interest to develop compounds that could activate the function of Slc12a8 in those specific neurons and prevent or treat age-associated sarcopenia and frailty." (PMID 39870672, 2025). "Additionally, our previous study revealed the importance of solute carrier family 12 member 8 (Slc12a8) in the LH in the pathogenesis of sarcopenia." (PMID 40955861, 2025).
bladder tumors (1 paper, 2021). "More importantly, we first used IHC to analyze SLC12A8 protein expression in normal tissues and bladder tumors, providing evidence for SLC12A8 as a potential diagnostic marker for BC." (PMID 34365894, 2021).
lung carcinoma (1 paper, 2024). "According to our previous transcriptomic analysis, PAH and lung cancer have three (C1QBP, COX6B1, and SLC12A8) common overregulated genes located in the transmembrane helix related to negative regulation of transcription by RNA polymerase II and chemical carcinogenesis-reactive oxygen species." (PMID 39791702, 2024).
cancer (7 papers, 2021 to 2026). A tumor composed of atypical neoplastic, often pleomorphic cells that invade other tissues. "In the present research, we used public cancer databases for data mining and found SLC12A8 mRNA overexpression in BC associated with poor prognosis." (PMID 34365894, 2021). "Actually, other SLCs, such as SLC38A1 and SLC12A8, are also involved in cancer development and drug resistance by regulating the AKT signaling." (PMID 39949345, 2025). "Cancer-associated fibroblasts (CAF) expressed well-known markers including FAP, COL1A1, COL10A1, MMP11, and CTHRC120,21, and other genes such as INHBA, SLC12A8, F2R, and COL12A1 in various organs." (PMID 38744958, 2024). "Further studies are needed to elucidate the precise functions of SLC12A8 in the context of cancer and determine its significance as a potential therapeutic target." (PMID 37775731, 2023). "Altered SLC12A8 expression levels have been observed in cancer cells, indicating its potential role in cancer biology." (PMID 37775731, 2023). "Among the 12 SLCs, we found that the SLC12A8 represents one of the most upregulated genes in cancer (TCGA tumor types vs." (PMID 37397501, 2023). "The chemokine signaling pathway, cell adhesion molecules, ECM receptors, and the cancer pathway related to tumorigenesis, invasion, and metastasis were significantly enriched in the group of high SLC12A8 expression." (PMID 34365894, 2021). "Reports about the specific function of SLC12A8 on cancer cells or normal cells proliferation and EMT were limited." (PMID 33364434, 2021). "Consistently, SLC12A8 overexpression was considered a prognostic factor of cancer-specific survival in GSE13507." (PMID 34365894, 2021). "In the GSE13507 cohort based on univariate Cox analysis, SLC12A8 overexpression was predicted poor cancer-specific survival in BC patients (HR = 1.2338, p < 0.01); however, it was not an independent factor by multivariable Cox analysis (HR = 0.6537, p = 0.2715)." (PMID 34365894, 2021). "In addition to its involvement in ion transport, SLC12A8 is involved in certain cancers." (PMID 37775731, 2023). "However, the exact mechanisms by which SLC12A8 contributes to cancer development and progression remain unknown." (PMID 37775731, 2023).
tumor (7 papers, 2021 to 2026). "Subsequently, we found that SLC12A8 was associated with multiple tumor immune cell infiltration and positively correlated with immune checkpoint molecules in BC." (PMID 34365894, 2021). "Cystatin A, a protein that interacts with SLC12A8, is a putative tumor suppressor that modulates extracellular matrix remodeling, cell adhesion, tumor invasion, and metastasis." (PMID 34365894, 2021). "GO & KEGG pathway analysis and GSEA results revealed that SLC12A8 mainly affects tumor progression by acting on tumor-related pathways, including NF-kb, PI3K-Akt, and Toll-like receptors." (PMID 34365894, 2021). "qPCR analysis of 25 groups of clinical tissues confirmed that the expression levels of SLC12A8 in tumor tissues were significantly greater." (PMID 34365894, 2021). "Moreover, all the CG probesets within the body region of SLC12A8 were positively correlated with gene expression in several tumor types." (PMID 37397501, 2023). "In conclusion, SLC12A8 might be an unfavorable prognostic biomarker in BC related to tumor immune cell infiltration." (PMID 34365894, 2021). "According to CIBERSORT, SLC12A8 may be involved in the complex tumor microenvironment by regulating CD4 + T memory cells, DC cells, macrophages (M0, M1, M2), neutrophils, γ δ T cells, and follicular T-helper cells." (PMID 34365894, 2021). "Moreover, the correlations of SLC12A8 expression with the tumor-infiltrating immune cells (TICs) in BC were explored using TIMER 2.0 and CIBERSORT." (PMID 34365894, 2021). "Furthermore, we found that SLC12A8 may affect the tumor microenvironment and may be a potential marker of immunotherapy response." (PMID 34365894, 2021). "Meanwhile, SLC12A8 may regulate ECM-receptor interaction, extracellular matrix organization, cell adhesion, and immunoglobulin binding to impact tumor microenvironment and immunity." (PMID 34365894, 2021). "Whether the relationship between SLC12A8 and tumor is related to the mechanism of immunity, signal transduction, and tumor microenvironment has not been clarified." (PMID 34365894, 2021). "However, no studies have been conducted on the effect of SLC12A8 on the tumor microenvironment." (PMID 34365894, 2021).
SLC12A8 also shares sentences with these, for which no sentence is quoted: acute myocardial infarction (2 papers); autism (1); autoimmune disease (1); bladder urothelial carcinoma (1); dyslipidemia (1); lymph node metastasis (1); ulcerative colitis (1).